MMP2 (matrix metallopeptidase 2)
Diseases named in the same sentence as MMP2 in open-access papers (continued):
Sharing a sentence is not in itself a finding about the gene and the disease.
sarcoma (continued). "However, we did not demonstrate directly whether the complex formation of CD73 and emmprin is essential for the regulation of MMP-2 production in co-cultures of sarcoma cells with fibroblasts." (PMID 31510956, 2019). "More recently, Eom and Kim reported that a methanol extract from A. pilosa inhibits cell invasion by decreasing the levels and activities of MMP-2 and MMP-9 in HT1080 human sarcoma cells." (PMID 35337161, 2022). "Chlorotoxin is a peptide which binds in a specific fashion with matrix metalloproteinase-2 (MMP-2), which is over-expressed in certain types of cancer such as brain, prostate, skin, sarcoma, among others and plays a role in cancer metastasis." (PMID 33381459, 2020). "Both matrices are derived from Engelbreth-Holm-Swarm mouse sarcoma, and contain growth factors (EGF, FGF, TGFβ, IGF), ECM proteins (laminin, collagen IV, entactin), proteases (MMP-2, MMP-9), and perlecan." (PMID 30805306, 2019). "In sarcoma, there is evidence for that the SDF-1 ligand induces chemotaxis across membranes, adhesion to endothelial cells, and matrix metalloproteinase 2 (MMP-2) expression." (PMID 31418125, 2019). "In conclusion, our results show that cytokines and inhibitors regulate MMP-2 and MMP-9 expression in adult sarcoma cell lines, suggesting the clinical value of targeting these proteases for management of sarcomas and their pathogenesis." (PMID 24085323, 2013). "Additionally, in this study based on ELISA and gelatin zymography techniques, they observed that both MMP-2 and MMP-9 have reduced activity in the media from miR-182-deleted sarcoma cells." (PMID 36980984, 2023). "Our results show that cytokines, mitogens, inducers and inhibitors have an up or down regulatory effect on MMP-2 and MMP-9 expression in adult sarcoma cell lines, suggesting these agents may be effective strategies to treat these cancers." (PMID 24085323, 2013). "Among all sarcomas (FISS and non-FISS), 17.64% of the tumors were negative and 82.36% were positive for MMP-2." (PMID 39061572, 2024). "Analysis of secreted paracrine factors revealed that MMP-2, TGF-β1 and MCP-1 were not detectable in cultures of parental (P) or bone-seeking (BO) cells alone, but were present in femur alone cultures and cocultures in concentrations comparable to those observed in sarcoma cultures." (PMID 19192289, 2009).
Cirrhosis (20 papers, 2010 to 2025). A chronic disorder of the liver in which liver tissue becomes scarred and is partially replaced by regenerative nodules and fibrotic tissue resulting in loss of liver function. "Thus, MMP-2 is a useful diagnostic test, especially when it comes to detecting cirrhosis." (PMID 24032040, 2013). "Compared with the GRS 0–4 group, patients with cirrhosis with GRS 5–8 exhibited increased levels of MMP2 (FDR <0.05), CCL1, and CXCL8 (p <0.05)." (PMID 40995436, 2025). "Patients with HCC with high scores had lower levels of interferon-gamma and CCL8 (false discovery rate <0.05), whereas patients with cirrhosis with high scores showed higher matrix metallopeptidase 2 (MMP2) levels (false discovery rate <0.05)." (PMID 40995436, 2025). "On the other hand, Q-BR exposed significant upregulation in the stained metalloproteinase protein MMP-2 compared to the cirrhosis control group which recorded reversed results." (PMID 36204229, 2022). "All of them except MMP2 were up-regulated in the cirrhosis condition being IL-6 the gene showing the largest extent of up-regulation." (PMID 31233564, 2019). "In established end-stage injury with cirrhosis there is increased expression of MMP-2, MMP-9, MMP-14 as well as TIMP-1 and TIMP-2." (PMID 25076423, 2014). "TGF-β1, collagen IV, laminin and MMP-2 had the ability to discriminate patients with significant fibrosis, while only collagen IV and laminin were able to discriminate those with cirrhosis." (PMID 27942306, 2010). "In addition, JWH-133 reduced levels of α-SMA and collagen and elevated levels of MMP-2 in the liver tissue of rats with cirrhosis in comparison with untreated rats with cirrhosis." (PMID 34708034, 2021). "Some hepatocytes adjacent to portal tracts in cirrhosis showed positivity for MMP-2." (PMID 27881141, 2016). "The highest serum CK-18 M30 and MMP-2 levels were measured in patients with cirrhosis." (PMID 24032040, 2013). "In addition to the effects of increased synthesis of collagen induction of cirrhosis also showed an increased expression of the enzyme matrix metalloproteinase 2 (MMP-2)." (PMID 22577570, 2012). "Therefore, we sought to determine expression of the rat genes Mmp2, Mmp9, Timp1 and Timp2 in the liver of CCl4-treated rats with different degrees of cirrhosis." (PMID 21813019, 2011). "MMP-2 at a cut off value of more than 742 ng/ml has a sensitivity of 85.7% and specificity of 71.4% in identifying significant fibrosis and at a cut off value of more than 747 ng/ml had a sensitivity of 85.7% and specificity of 64.6% in identifying cirrhosis." (PMID 27942306, 2010). "In conclusion, TGF-β1, collagen IV, laminin and MMP-2 may be used to predict significant fibrosis and/or cirrhosis in children with chronic hepatitis B and C. Among them, collagen IV was the most sensitive and specific." (PMID 27942306, 2010). "When stratified into lean and overweight cirrhosis groups, patients with GRS 5–8 consistently showed higher levels of MMP2 in both groups compared with GRS 0–4." (PMID 40995436, 2025). "After erlotinib treatment, expression of antifibrotic pathways, including Mmp2, Mmp3, and Mmp8, were enhanced in PCLS from CDAHFD-induced cirrhosis, while expression of profibrotic pathways, including Mmp9 and Mmp13, were hampered." (PMID 39445861, 2024). "Most liver cells have high levels of MMP-2, -3, -7, and -16 during viral hepatitis and HCC; MMP-8, -9, -10-, -12, -13, -14, and MMP-16 during HCC and cirrhosis; and MMP-24 during liver regeneration." (PMID 37509493, 2023). "Serum from HCV-HCC patients showed higher levels of MMP-2 and pentraxin-3 as well, but, in addition, exhibited increased levels of IL-6 and HGF in HCC compared to HCV-cirrhosis patients." (PMID 36230823, 2022). "Sera from HBV-HCC patients were characterized by higher MMP-2 and pentraxin-3 levels, with a trend toward lower cytokine and chemokine concentrations, when compared to HBV patients with cirrhosis." (PMID 36230823, 2022).
Cirrhosis (continued). "Some intermediate hepatocyte-like cells (IHLCs) adjacent to portal tracts from patients with cirrhosis showed immunopositivity for MMP-2 rather than EpCAM." (PMID 27881141, 2016). "Upon detailed assessment, cytokine levels and cirrhosis etiology revealed that HBV-cirrhosis—regardless of antiviral therapy—had a 3-fold increase in IFN-γ, TRAIL and CXCL1 (GRO-α) levels and up to 3-fold decrease in MMP-2, CXCL12, IL2RA, IL-6Rα, CCL2 (MCP1) and CCL21 (6kine) levels." (PMID 36230823, 2022).
lymphoma (20 papers, 2007 to 2025). A malignant (clonal) proliferation of B- lymphocytes or T- lymphocytes which involves the lymph nodes, bone marrow and/or extranodal sites. "Patients with newly diagnosed, active lymphoma had higher levels of MMP-2/TIMP-2 complex and lower levels of TIMP-2, compared to healthy individuals." (PMID 32751899, 2020). "Four years later, the same team published a manuscript in which MMP-2/TIMP-2 complex levels were measured in plasma obtained from 126 patients with lymphomas (HL = 31, non-Hodgkin lymphoma (NHL) = 95) and 44 healthy controls." (PMID 32751899, 2020). "Like BL cells, λ-MYC lymphoma cells, especially when apoptotic, were able to activate MMP2 and MMP12 expression in macrophages in vitro and promote the expression of a variety of SS-TAM markers in bone marrow-derived macrophages (BMDMs)." (PMID 25702581, 2015). "The mRNA expression of MMP-9 and MMP-2 was studied as an inducer of angiogenesis in the tumor microenvironment of metastatic liver of lymphoma bearing mice." (PMID 24932681, 2014). "Previously published data have shown bi-directional signaling during contact between tumor cells and target tissue, in particular lymphoma cells and the endothelial cells can result in high expression of MMP-2 and MMP-9 in both cell types." (PMID 19662219, 2007). "In addition to the effects of apoptotic lymphoma cells on TAMs, we also report that apoptosis-induced human and murine lymphoma cells upregulate and process MMP2 and MMP12." (PMID 25702581, 2015). "Given the pleiotropic functions of MMPs in tumor growth and/or progression and the consistent upregulation of MMP2/12 in macrophages exposed to apoptotic lymphoma cells, we began analyzing the expression and processing of macrophage MMP2 and MMP12 at the protein level." (PMID 25702581, 2015). "Furthermore, we demonstrate that, upon induction of apoptosis, lymphoma cells not only activate expression of the tumor-promoting matrix metalloproteinases MMP2 and MMP12 in macrophages but also express and process these MMPs directly." (PMID 25702581, 2015). "Viable lymphoma cells may also contribute to MMP2 and MMP12 upregulation, but it is noteworthy that “viable” populations contained small numbers of constitutively apoptotic cells." (PMID 25702581, 2015). "A different post-transcriptional regulation of MMP-2 or indirect mechanisms of activation may be hypothesised in lymphomas." (PMID 23641796, 2013). "MMP-2 and MMP-9, gelatinases which are capable of degrading type IV collagen, are known to be activated in lymphomas, and their activation is considered to be related to the metastasis of lymphomas." (PMID 36357882, 2022). "MMP-2 and TIMP-2 mRNA levels in the healthy control lymph nodes were significantly higher than in lymphomas (p<0.05)." (PMID 23641796, 2013). "Both latent and active forms of MMP-2 and MMP-9 were undetectable at gelatine zymography in lymphoma samples." (PMID 23641796, 2013). "In contrast, expression of MMP-2 and MMP-9 in other lymphoma subtypes appears less pronounced than in epithelial malignancies, likely reflecting differences in stromal composition; fibroblasts dominate ECM remodeling in carcinomas, whereas lymphoid stroma is more cellularly heterogeneous." (PMID 41303704, 2025). "Specifically, MMP-2 and MMP-9 are central to ECM remodeling across multiple lymphoma subtypes." (PMID 41303704, 2025). "Upregulation of MMP-2 and MMP-9 contributes to high invasion and infiltration of lymphoma cells." (PMID 35685474, 2022). "Similarly, in this study, vitreous MMP-2 was significantly higher and MMP-9 also tended to be high in lymphoma patients with extraocular involvement." (PMID 36357882, 2022). "Since MMPs, especially MMP2 and MMP9 play important role in tumor invasion and in metastatic process, and are activated in TME in DLBCL, we next evaluated the stimulatory effect of lymphoma TEXs on MMP2 and MMP9." (PMID 30103789, 2018).
lymphoma (continued). "Remarkably, in the course of these studies, we observed that apoptotic lymphoma cells directly upregulated and processed MMP2 and MMP12 polypeptides in the absence of other cell types in both murine and human models." (PMID 25702581, 2015). "We observed marked upregulation of both MMP2 and MMP12 by apoptotic lymphoma cells." (PMID 25702581, 2015). "A possible limit in the study is the lack of lymphoma tissue; so far, further experiments should be directed to identify the catalytic activity of MMP-9 and MMP-2 in B-cell and T-cell lymphomas." (PMID 23641796, 2013).
brain tumor (19 papers, 1999 to 2025). "Urine samples from brain tumor patients showed significant elevations in MMP-2, MMP-9, MMP-9/NGAL, and VEGF compared to controls (all p < 0.001), with MMP-2 and VEGF providing the best diagnostic accuracy when combined." (PMID 40265458, 2025). "Excessive migration and invasion are characteristic of malignant brain tumors, and matrix metalloproteinases (MMPs), especially MMP2 and MMP9, play an essential role in the invasion of GBM cells." (PMID 36922509, 2023). "In brain tumors, MMP2 serves as a predictor of tumor recurrence." (PMID 24156018, 2013). "The results we show here highlights the importance of hypoxic mechanism in brain tumours and the high level of overexpression of angiogenic factors as HIF1A, VEGFA, and MMP2 that are implicated in metastasis could be target molecules in those tumour types." (PMID 22570651, 2012). "Research has increasingly shown that MMPs, particularly MMP-2 and MMP-9, influence immune cell trafficking, cytokine release, and immune suppression in brain tumors, potentially by modulating the expression and activity of immune checkpoint molecules." (PMID 40265458, 2025). "Recent studies have shown that MMP-2 and MMP-9 inhibition can enhance the penetration of chemotherapy drugs across the BBB, potentially improving their efficacy in treating brain tumors." (PMID 40265458, 2025). "Gelatinase-A (MMP-2) and gelatinase-B (MMP-9) are highly expressed in patients with WHO grade III brain tumors." (PMID 32152825, 2020). "MMP2, for instance, can not only induce tumor cell invasion by degrading ECM but promote tumor cell proliferation by enhancing vessel maturation and function in brain tumors." (PMID 33596197, 2021). "Radiation-induced imbalance between MMP-2 and tissue inhibitors of MMP-2 may disrupt the blood–brain barrier, leading to cognitive impairment in brain tumor patients." (PMID 33134822, 2020). "In this study, MMP-2, MMP-9, and MMP-9/NGAL, in addition to the pro-angiogenic molecule vascular endothelial growth factor (VEGF), were found to be elevated in the urine of 28 brain tumor patients relative to controls (p < 0.001)." (PMID 24400253, 2013).
Cognitive impairment (19 papers, 2014 to 2025). Abnormal cognition is characterized by deficits in thinking, reasoning, or remembering. "Moreover, we aimed to evaluate the influence of studied MMP2 polymorphisms on the age of onset and on the level of cognitive impairment expressed as the total score of Montreal cognitive assessment (MoCA)." (PMID 37109410, 2023). "Serum MMP-2 in acute phase emerges as a promising biomarker: its level correlates with the recurrence of cerebral amyloid angiopathy/intracerebral hemorrhage, which helps to evaluate the risk of cognitive impairment." (PMID 36232390, 2022). "While MMP-2 activity is decreased in AD patients and those with mild cognitive impairment, suggesting a potential protective role against Aβ accumulation." (PMID 40444055, 2025). "SB-3CT, a selective MMP2/9 inhibitor, has been shown to mitigate rotenone-induced cognitive deficits in mice by targeting microglia-mediated blood–brain barrier disruption and neuronal apoptosis via MMP2/9, highlighting its mechanistic relevance to PD pathogenesis." (PMID 40422771, 2025). "The present study strongly suggests that SerpinA3N and MMP2 specific inhibitor may be a new therapeutic agents against neuronal apoptosis and cognitive impairments in neurotrauma." (PMID 33014432, 2020). "Based on the positive effects of MMP-2 on cognitive efficacy in recurrent depression, how elevated MMP-2 levels in patients with schizophrenia influence cognitive deficits needs further investigation." (PMID 38429778, 2024). "A study on the Tg-APP/PS1 mouse AD model reported that hyperoxygenation increases the production of MMP-2, MMP-9, and tPA, leading to reduction of Aβ deposition in the brain and rescued cognitive impairment." (PMID 37109410, 2023). "Hyperoxygenation treatment upregulates MMP-2, MMP-9 and tPA expression which reduces β-amyloid accumulation and rescues cognitive impairment in APP/PS1 transgenic mice." (PMID 36232390, 2022). "In previous studies, high expression of the MMP-2 gene on mRNA and protein levels in recurrent depressive disorders reported positive effects on cognitive efficiency, such as working memory and executive and attentional functions, and inhibition of MMP-2 attenuated cognitive impairment in aged mice." (PMID 38429778, 2024). "Indeed, activation of MMP9, but not of MMP2, was reported in serum and brain samples of patients with mild cognitive impairment and with AD." (PMID 28912710, 2017). "However, the lack of correlation between MMP-2 and TNF-α and cognitive function in our study was intriguing and suggests that the cognitive deficits in TRS and CMS may not be mediated by a single mechanism." (PMID 38429778, 2024).
kidney damage (19 papers, 2007 to 2025). "Notably, the reduced activity of MMP-2 has been associated with kidney damage in diabetic kidney tissue." (PMID 39051237, 2024). "One may suggest that Mmp2 deficiency decreases vasoconstriction and thus reduces kidney damage in UUO." (PMID 26673451, 2015). "Increased MMP-2 levels, in particular in urine, have been related to increased risk of nephropathy." (PMID 19758433, 2009). "Mmp2 has also been found to cleave adrenomedullin, resulting in production of a vasoconstrictor peptide, and this may be an underlying mechanism that leads to kidney damage." (PMID 26673451, 2015). "On the other hand, MMP-2, a gelatinase that degrades type IV collagen, is essential for basement membrane homeostasis and has been identified as a marker of kidney damage in models of CKD." (PMID 40649789, 2025). "Both MMP-2 and MMP-9 are implicated in vascular damage processes and are associated with kidney damage, making their elevation particularly unfavorable in diabetic patients." (PMID 39685536, 2024). "Nebivolol attenuated kidney damage, reducing the expression and level of MMP-2 and MMP-9, as indicated in a rat model of ischemia-reperfusion injury." (PMID 35629096, 2022). "Among the different types of MMPs, MMP-1, MMP-2, and MMP-3 have been identified as particularly important in the progression of kidney damage." (PMID 40649789, 2025). "Therefore, MMP-2 could potentially be developed into a protein biomarker for nephropathy in SIDD." (PMID 36402758, 2022). "For example, the most frequently studied MMPs in HF and kidney damage are MMP-2 and MMP-9, out of which MMP-9 is believed to have a profibrotic effect whereas MMP-2 has antifibrotic effects." (PMID 34359993, 2021). "In the DM population, the expression of MMP-2 and MMP-9 is altered, which contributes to microangiopathic and macroangiopathic complications, such as nephropathy, with MMP-2 being a good index of microangiopathy severity and MMP-9 being a good marker of macroangiopathy." (PMID 33419373, 2020). "The results indicate that plasma MMP-2 may play a role in the pathogenesis of equine colic and urinary MMP-9 in equine kidney damage." (PMID 17244354, 2007).